ERCC1 (ERCC excision repair 1, endonuclease non-catalytic subunit)
Diseases named in the same sentence as ERCC1 in open-access papers (continued):
Sharing a sentence is not in itself a finding about the gene and the disease.
colorectal cancer (continued). "In colorectal cancer, for example, polymorphisms in genes such as XRCC1 and ERCC1 have been linked to variations in recurrence‐free and overall survival, underscoring their prognostic relevance." (PMID 40833230, 2025). "Currently, the expression of DNA repair genes such as the enzyme O-6-methylguanine-DNA methyltransferase (MGMT) and Excision Repair Cross-Complementation Group 1 (ERCC1) plays a potential role in colorectal cancer progression." (PMID 37510370, 2023). "In our previous study, we also reported that the overexpression of ERCC1 leads to resistance to radiation in colorectal cancer." (PMID 37296596, 2023). "The methylation of MGMT, alone or combined with ERCC1, is predictive for poor prognosis, short overall survival and chemotherapy response in colorectal cancer." (PMID 37510370, 2023). "The current work confirmed a significant association between ERCC1 and MGMT methylation, either alone or combined with poor prognosis, relapse and low survival in colorectal cancer patients." (PMID 37510370, 2023). "For further verification, we exposed HCT116-Tet-on and COLO205-Tet-on heterotopic cancer animal models to radiation and observed that ERCC1 overexpression increased colorectal cancer tumor radioresistance in both." (PMID 36230725, 2022). "We then used an ectopic colorectal cancer animal model to investigate the effects, if any, of ERCC1 overexpression on colorectal cancer radiation sensitivity." (PMID 36230725, 2022). "Ovarian, non-small cell lung, and colorectal cancer patients have demonstrated an inverse relationship between response to CP and ERCC1 mRNA levels." (PMID 36499737, 2022). "To select colorectal cancer cells with low ERCC1 expression, we analyzed the expression of ERCC1 mRNA and the protein in HEK293, HCT116, SW620, COLO205, and SW480 cell lines." (PMID 36230725, 2022). "In patients with colorectal cancer ERCC1, ERCC2, ERCC5 and DDB2 genes are more expressed in tumor tissue than in matched normal tissue, while ERCC4 is downregulated." (PMID 35955506, 2022). "We previously reported finding a high correlation between ERCC1 gene overexpression and radiation response in colorectal cancer patients." (PMID 36230725, 2022). "Curcumin can overcome L-OHP resistance in colorectal cancer cells through its effects on miR-409-3p mediated ERCC1 expression." (PMID 33014113, 2020). "In the current study, we examined the association of SNPs in the genes XRCC1-rs25487, ERCC1-rs11615, ERCC2-rs238406, and ERCC2-rs13181 with colorectal cancer (CRC) risk, relapse-free survival (RFS), overall survival (OS), and toxicity during chemotherapy." (PMID 32397974, 2020). "Mallick and coworkers showed that the induction of ERCC1 is more important than baseline ERCC1 expression as a marker of oxaliplatin resistance in human colorectal cancer cells lines." (PMID 25505920, 2014). "Aim was to explore the association of ERCC1 and TS mRNA levels with the disease free survival (DFS) in Chinese colorectal cancer (CRC) patients receiving oxaliplatin and 5-FU based adjuvant chemotherapy." (PMID 25175730, 2014). "Resistant human colorectal cancer cell lines (among them the HT 29) show a significant induction in mRNA and protein levels of ERCC1 when exposed to oxaliplatin, which is in contrast to what occurs with sensitive cell lines." (PMID 25505920, 2014). "Scoring guidelines to aid in the evaluation of ERCC1 tumor expression were developed and evaluated in archival formalin-fixed paraffin embedded colorectal cancer specimens." (PMID 24603753, 2014). "The aim of the current investigation is to determine the presence, frequency and prognostic impact of ERCC1 or ERCC4 gene copy number alterations in colorectal cancer (CRC)." (PMID 24144331, 2013). "Here, ERCC1 and BRCA1, which are linked to lymph node metastasis (LNM) in colorectal cancer (CRC), were evaluated in primary CRC samples from Chinese patients with LNM (LNM CRC) or without LNM (non-LNM CRC)." (PMID 23496813, 2013).
colorectal cancer (continued). "Polymorphisms in the genes of GSTP1, ERCC1, XPD, and TS were associated with overall survival in patients with refractory advanced colorectal cancer who received 5-FU/oxaliplatin combination chemotherapy." (PMID 15213713, 2004). "We have compared the frequency of polymorphisms in the NER genes, XPD, XPF, XPG, ERCC1; in the BER gene, XRCC1; and in the RR gene, XRCC3; in colorectal cancer patients and in a control group." (PMID 12865926, 2003). "In this study, we have compared the frequency of polymorphisms in the NER genes (XPD, XPF, XPG, ERCC1), and in XRCC1 and XRCC3 in colorectal cancer patients and a control group." (PMID 12865926, 2003). "So far, there have been only limited studies focused on ERCC1 methylation in colorectal cancer." (PMID 37510370, 2023). "Therefore, we also confirmed it enhanced the effect of chemotherapy and radiation therapy by silencing ERCC1 in colorectal cancer cells." (PMID 37296596, 2023). "Thus, currently targeted therapy regarding ERCC1 has evolved for MUTYH, which is a glycosylase involved in the BER pathway and associated with colorectal cancer, and for MTHFR, interacting with folate synthesis and being prognostic in various cancers." (PMID 36497451, 2022). "There was no meta-analysis focused on the diagnosis of colorectal cancer with ERCC1 rs11615 variant." (PMID 36277013, 2022). "To confirm the effects of ERCC1 expression on CCRT efficacy, we induced ERCC1 overexpression in colorectal cancer cells and in an ectopic carcinoma animal model prior to radiation exposure, and we found evidence that ERCC1 overexpression triggered resistance to radiotherapy." (PMID 36230725, 2022). "This phenomenon indicates that the overexpression of ERCC1 could increase the proliferation and migration ability of colorectal cancer cells in a radiation-irradiated environment." (PMID 36230725, 2022). "Combined, our results suggest that ERCC1 overexpression may serve as a suitable CCRT prognostic marker for colorectal cancer patients." (PMID 36230725, 2022). "In his study, ERCC1 rs2298881 polymorphism rather than rs11615 is associated with an increased risk of colorectal cancer." (PMID 36277013, 2022). "Our in vitro and in vivo results indicate that ERCC1 overexpression triggered colorectal cancer radioresistance; therefore, we believe that ERCC1 levels may affect chemotherapy and radiation therapy efficacy via DNA repair." (PMID 36230725, 2022). "The results of this study confirmed that the expression of ERCC1 in HCT-116/L-OHP cells was abnormally increased, as were the expression of Bcl-2, GST-π, MRP, P-gp, and survivin, indicating that the resistance of colorectal cancer cells to L-OHP is mediated through ERCC1." (PMID 33014113, 2020). "The largest study with a pre-planned analysis of ERCC1 gene variants in colorectal cancer patients was the TOSCA trial, in which none of the studied polymorphisms showed association with toxicity or outcome." (PMID 30646508, 2019). "The genotypes of ERCC1 have been shown to be associated with other types of cancer, including colorectal cancer, bladder cancer, esophageal cancer, but not breast cancer, not to mention TNBC." (PMID 30096175, 2018). "In conclusion, we revealed that heterogeneity of DPD, TP, and VEGF expression may exist in colorectal carcinomas in which the depth had advanced and that ERCC-1 and VEGF may be biomarkers predicting recurrence after curative operations." (PMID 23577026, 2013). "Finally, siRNA-mediated silencing of ERCC1 (excision repair cross complementing group 1) sensitized human colorectal cancer cells to oxaliplatin-induced cell death." (PMID 22954140, 2012). "The association between the three polymorphisms, ASE-1 G-21A, RAI IVS1 A4364G and ERCC1 Asn118Asn and colorectal cancer was not statistically significant different (all P > 0.25) between genders." (PMID 18289367, 2008).
colorectal cancer (continued). "The genomic polymorphisms XPD-751, ERCC1-118, GSTP1-105, and TS-3′UTR may be useful in predicting overall survival and time to progression of colorectal cancer in patients who receive 5-FU/oxaliplatin chemotherapy." (PMID 15213713, 2004). "In addition, we analyzed the effect of ERCC1 on colorectal cancer patients in the GEPIA database." (PMID 36230725, 2022). "In addition, there was no meta-analysis focused on the diagnosis of colorectal cancer with ERCC1 rs11615 variant." (PMID 36277013, 2022). "An ERCC1 polymorphism, which induced a codon change from common usage codon AAC to AAT, has also been found to suppress ERCC1 expression, and the objective response rate was much higher after oxaliplatin and 5-fluorouracil combination chemotherapy in colorectal cancer patients." (PMID 24624997, 2014). "Considering all these things, we found it rational to investigate the correlation between the methylation status of ERCC1 and MGMT, prognosis, survival and therapeutic response in colorectal cancer patients." (PMID 37510370, 2023). "There are several reports on the methylation profile of ERCC1 and MGMT in colorectal cancer patients from different populations." (PMID 37510370, 2023). "Data from clinical staining studies have shown that colorectal cancer patients with a poor prognosis following the combination of FOLFOX and radiation exposure often exhibit high levels of ERCC1 overexpression." (PMID 36230725, 2022). "In patients with stage 3 colorectal cancer treated with OXP, those with ERCC1 positive tumours were found to have a lower 5-year disease free and overall survival than those with ERCC1 negative tumours." (PMID 36499737, 2022). "The results showed the expression of ERCC1 in HCT116 and COLO205 to be lower than other colorectal cancer cell lines; therefore, we used HCT116 and COLO205 for the establishment of Tet on ERCC1 stable cell lines." (PMID 36230725, 2022). "In a six-line colorectal cancer in vitro study, OXP cytotoxicity was found to be predicted by ERCC1 levels, and in cells that were able to maintain lower levels of XPA, OXP DNA adducts had a stronger cytotoxic effect." (PMID 36499737, 2022). "We already stated the significance of ERCC1 SNPs as prognostic biomarkers in NSCLC, ovarian and colorectal cancer." (PMID 33266377, 2020). "ERCC1 has demonstrated promise as a predictive and prognostic marker in solid tumors such as non-small cell lung (NSCLC), ovarian, pancreatic and colorectal cancer." (PMID 31565185, 2019). "In the present study, the expression of NER genes (XPC, XPA, XPG, XPF, ERCC1, and XPD) was measured in human colorectal cancer and the corresponding normal tissues." (PMID 30109214, 2018). "Although ERCC1 has a role as a prognostic marker in NSCLC, only a few studies have evaluated its role as a prognostic marker in colorectal cancer and most of the previous data were generated in the metastatic setting of cancer." (PMID 28767665, 2017). "The promoter methylation of ERCC1 and MGMT is an essential event in cancer progression, spread, relapse, and could be clinically useful in assessing colorectal cancer progression and survival." (PMID 37510370, 2023). "However, our previous studies indicated that the high expression of Excision Repair Cross-Complementation Group 1 (ERCC1) contributes to lower efficiency of chemotherapy, poor response to radiotherapy, and poor prognosis in colorectal cancer." (PMID 37296596, 2023). "In addition, the pharmacokinetics of the ERCC1–XPF inhibitor also needs to be confirmed, and cancers should be treated with CCRT such as colorectal cancer in the future." (PMID 37296596, 2023). "In addition to their role in cancer prevention, ERCC1 and MGMT genes were considered as markers for the therapeutic response of many types of cancer, including colorectal cancer." (PMID 37510370, 2023).
colorectal cancer (continued). "Further research is required to confirm ERCC1 expression detection as an appropriate predictor of CCRT treatment efficacy, and to test the possibility of combining ERCC1 inhibitors to improve CCRT efficacy for colorectal cancer patients." (PMID 36230725, 2022). "ERCC1, RRM1, RRM2, and hENT-1 have been proposed as potential predictive biomarkers of treatment response in several types of tumors, including lung, pancreatic, ovarian, and colorectal cancer." (PMID 34353292, 2021). "Curcumin (Cur) can reverse the drug resistance of cancer cells, but its effects on ERCC1 expression and miRNA profiles in colorectal cancer have not been studied." (PMID 33014113, 2020). "In particular, our results demonstrated a substantial reduction in the transcript levels of ERCC1 and XPD in all MPM cell lines, as previously detected in a cisplatin-resistant carcinoma cell line treated with 5-FU, as well as in colorectal cancer cell lines treated with pemetrexed." (PMID 21970874, 2011). "Although ERCC1 was not represented in the 9K chips used in this study, our microarray analyses identified at least four genes involved in DNA repair mechanisms that were significantly correlated with the ability of oxaliplatin to induce apoptosis in colorectal cancer cells." (PMID 15545975, 2004).
gastric cancer (47 papers, 2007 to 2024). A primary or metastatic malignant neoplasm involving the stomach. "Low mRNA levels of ERCC1 in primary gastric cancer have been associated with a higher overall response rate and longer survival following cisplatin treatment." (PMID 39516666, 2024). "In this case, the high expression of ERCC1 is associated with the mechanism that influences tumor behavior, with the ability of this gene to repair DNA damage in gastric cancer cells." (PMID 37895364, 2023). "Deletion of ERCC1 protein is associated with cancer susceptibility and has been reported as a biomarker for platinum resistance in colorectal and gastric cancer patients." (PMID 36386844, 2022). "The ERCC1 SNP rs3212986 is also associated with lung and gastric cancer and affects mRNA levels, transcriptional stability of mRNA and ERCC1 levels." (PMID 36497451, 2022). "A previous study has also reported that ERCC1 rs11615 was associated with the response to chemotherapy and clinical outcome in cases of gastric cancer." (PMID 26622786, 2015). "The authors conducted a study including 447 patients in China, and reported that the T allele of ERCC1 rs11615 decreased the risk of mortality from gastric cancer." (PMID 26622786, 2015). "This analysis revealed that ERCC1 rs11615 was associated with OS of gastric cancer: Patients with the TC+CC genotypes had a longer survival time compared with those with the common TT genotype (33.20 vs. 23.30 months; log-rank P=0.017)." (PMID 26622786, 2015). "The current study revealed that ERCC1 rs11615 is associated with the outcome in cases of gastric cancer treated with chemotherapy." (PMID 26622786, 2015). "Further studies are required in order to confirm the association between ERCC1 rs11615 and clinical outcome in cases of gastric cancer." (PMID 26622786, 2015). "False-positive report probability for Association between overall survival in gastric cancer patients and the genotypes and haplotypes of ERCC1 and ERCC2 variants." (PMID 24023723, 2013). "Nevertheless, some greater FPRP values (>0.2) were observed for some other significant associations in stratified analyses (e.g. ERCC2 rs13181 and ERCC1 rs3213986 variant genotypes with gastric cancer OS)." (PMID 24023723, 2013). "When we combined these three selected ERCC1 SNPs, we found that patients with 2–3 risk genotypes had significantly increased risk of gastric cancer compared with those with 0–1 risk genotypes." (PMID 23166636, 2012). "Stratification analysis for associations between ERCC1 variant genotypes and gastric cancer risk in an Eastern Chinese population." (PMID 23166636, 2012). "Specifically, two case-control studies reported the association between ERCC1 rs11615 variant genotypes and gastric cancer risk, including one study of 126 cases and another of 314 cases in Italian populations." (PMID 23166636, 2012). "False-positive report probability values for associations between the risk of gastric cancer and the frequency of genotypes of the ERCC1 gene." (PMID 23166636, 2012). "For example, low gene expression levels of ERCC1 were associated with a superior response to 5-FU and cisplatin chemotherapy (FP) in primary gastric cancer, and ERCC1 protein expression levels were found to be inversely associated with response." (PMID 19259093, 2009). "Decreased ERCC1 expression was associated with a superior response to 5-FU/cisplatin in primary intact gastric cancer patients." (PMID 19259093, 2009). "Studies on ERCC1 rs3212961 were controversial, although the rs3212961 C allele was associated with a shorter overall survival in gastric cancer patients and a higher risk for non-Hodgkin lymphoma development, which were consistent with results of the present study." (PMID 35627777, 2022). "Additionally, in gastric cancer ERCC1 mRNA expression from tumor tissue was conversely associated with cisplatin response." (PMID 31504065, 2019).